GRB10 (growth factor receptor bound protein 10)
Diseases named in the same sentence as GRB10 in open-access papers (continued):
Sharing a sentence is not in itself a finding about the gene and the disease.
tumor (continued). "Grb10 restoration significantly decreased proliferation by the Nf1 null 881 tumor cells, and to a lesser extent, reduced cell proliferation in V16HRas-transformed human astrocytes." (PMID 26000738, 2015). "Functionally, restoring Grb10 protein in Nf1 null tumors suppressed tumor growth in a MAPK-dependent mechanism." (PMID 26000738, 2015). "Western blotting demonstrated that Grb10 protein was undetectable in all 12 tumor cell lines, including the 867 cell line." (PMID 26000738, 2015). "This work demonstrates a new role for an imprinted gene in tumor formation, and shows that Grb10 functions to negatively regulate Ras signaling and suppress hyperproliferation." (PMID 26000738, 2015). "Expression analysis of these lines revealed decreased Growth factor receptor bound protein 10 (Grb10) mRNA in Nf1 null tumor cell lines compared to controls." (PMID 26000738, 2015). "Expression of a constitutively activated MEK rescued tumor cells from Grb10-mediated reduction in colony formation." (PMID 26000738, 2015). "Grb10 restoration in Nf1 mutant tumor cells reduced colony formation, proliferation, and suppressed Ras signaling, suggesting Grb10’s tumor suppressive effects are mediated by modulating Ras pathway activation." (PMID 26000738, 2015). "In the tumor cell lines tested here, Grb10-mediated growth suppression is largely mediated by dampening MAPK rather than PI3K signaling, possibly reflecting intrinsic dependencies of these tumors on activated MAPK signaling." (PMID 26000738, 2015). "This activation pattern contrasts with the signaling consequences of Grb10 restoration observed in tumor cells." (PMID 26000738, 2015). "Grb10 restoration significantly decreased pERK levels and proliferation in these tumor cells, indicating that Grb10-mediated growth suppression does not require Nf1 loss." (PMID 26000738, 2015). "For instance, BCL7A and GRB10, which were found to be protective factors in certain cancers, are known to regulate immune-related pathways and cellular signaling, potentially enhancing anti-tumor immunity and suppressing oncogenic activity." (PMID 39867577, 2024). "Our study is the preliminary report demonstrating the role of GRB10 as a tumor suppressor in SCLC." (PMID 39223679, 2024). "Our results thus suggest that in SCLC, GRB10 may thus act as a tumor suppressor and one of the ways it may be acting is through the regulation of Wnt signaling pathway." (PMID 39223679, 2024). "More in keeping with its growth inhibitory role during development there is convincing evidence that GRB10 acts as a tumour suppressor in at least two cases, that of clear cell renal cell carcinoma and in tumours from a cancer-prone mouse model heterozygous for the Neurofibromatosis 1 (Nf1) gene." (PMID 39343875, 2024). "ATO and APA may be mediating its action through the stabilization of GRB10 thus acting as a tumor suppressor." (PMID 39223679, 2024). "In addition, we found that tumor growth was slower in a mice xenograft model with knock down of GRB10 expression." (PMID 37179120, 2023). "However, recent studies have shown that GRB10 was abnormally expressed in various cancers, and changes in its expression were closely related to tumor formation and progression." (PMID 37179120, 2023). "Knockdown of GRB10 significantly reduced subcutaneous tumor weight and volume." (PMID 37179120, 2023). "Therefore, further research is required to reveal the function of GRB10 in oncogenesis and tumor progression in the different tumor types." (PMID 35790975, 2022). "Taken together, the expression of GRB10 was positively correlated to tumor growth." (PMID 35790975, 2022). "Although this was only a correlative analysis, a reading of relatively HuD high GRB-10 high ARL6IP1 high tumors may be indicative of the population of tumor types that we have been studying." (PMID 35012594, 2022). "The expression of GRB10 was positively correlated to the tumor grades." (PMID 35790975, 2022).
tumor (continued). "In addition, silencing of GRB10 expression inhibited cell growth, colony formation, invasion, migration, cell cycle, and tumor formation." (PMID 35790975, 2022). "We found that 14% of genes showed ASE in one or more cell lines and identified allelic switching of the potential cell survival genes DLX5, GRB10, and SVOPL on chromosome 7, whereby the most abundantly expressed allele in the normal tissue is the lowest expressed allele in the tumor and vice versa." (PMID 31093489, 2019). "Here we focused on the correlation of myeloid IGF1R, IRS1, and GRB10 with human tumor progression." (PMID 29973593, 2018). "Indeed, the mRNA and protein expression of IGF1R, IRS1, and GRB10 was increased in Gr-1+CD11b+ cells sorted from spleens of 4T1 tumor-bearing mice compared with that from healthy control mice." (PMID 29973593, 2018). "When restored, Grb10 suppressed tumor growth by down-regulating Ras signaling." (PMID 26000738, 2015). "Given Grb10’s functional connection to well-described tumor promoting signal transduction pathways, the literature suggests that Grb10 function could contribute to cancer development." (PMID 26000738, 2015). "Analysis of primary tumor samples identified 19 tumors from Nf1+/- mice in which Nf1 and Grb10 status could be co-determined." (PMID 26000738, 2015). "Grb10 restoration in Ras-transformed human astrocytes decreased cell proliferation, suggesting that even in cells expressing mutant Ras, Grb10 levels influence tumor growth." (PMID 26000738, 2015). "Grb10 expression was confirmed by immunoblotting, which showed that Ras-transformed human astrocytes demonstrated marked overexpression of Grb10 compared to 881 tumor cells." (PMID 26000738, 2015). "We assessed cell proliferation to determine whether similar to the MEFs and Nf1 mutant tumor cell lines Grb10 expression suppressed cell proliferation of Ras-transformed cells." (PMID 26000738, 2015). "The observed expression pattern may be relevant to the tumour suppressor role proposed for Grb10 in small cell renal cell carcinoma, a prevalent adult kidney cancer thought to arise predominantly from the proximal tubule." (PMID 25551289, 2014). "For instance, BCL7A and GRB10 showed protective roles in some cancers, possibly through mechanisms such as enhancing immune infiltration or suppressing oncogenic pathways, while THEM4, TDRD9, and KLRG1 acted as risk factors in others, potentially by inhibiting tumor suppressor functions." (PMID 39867577, 2024). "GSCs represent a cell subpopulation relevant for the tumor resistance to radiations and release EVs able to polarize microglial cells towards a pro-tumoral phenotype, specifically by transferring miR-504 that inhibits the putative onco-suppressor gene grb10 (growth factor receptor-bound protein 10)." (PMID 36361947, 2022). "Indeed, the chromosome alterations affecting the H19, KCNQ1OT1, PLAGL1 and GNAS DMRs also affected one or more WT driver genes in all analyzed cases, and the chromosome variants affecting the MEST, GRB10 and MEG3 DMRs also affected tumor driver genes in at least 83% of cases." (PMID 33217932, 2020). "However, immunoblotting for total Grb10 protein demonstrates absence of Grb10 protein in all tumor cell lines, including 867, suggesting that Grb10 loss in the 867 cell line results from alternative, possibly post-translational mechanisms." (PMID 26000738, 2015). "Allelic distributions of the 5 different GRB10 isoforms and the 3 different MEST isoforms in paired normal and tumor samples were compared." (PMID 31093489, 2019). "Interestingly, the Grb10 gene localizes to a region involved with LOH, suggesting that genetic loss of the expressed Grb10 allele may underlie the absence of Grb10 transcripts in Nf1 mutant tumor cell lines." (PMID 26000738, 2015). "Although Grb10 levels influence both PI3K and MAPK signaling in untransformed MEFs, in our tumor lines MAPK pathway activation was suppressed by Grb10 restoration." (PMID 26000738, 2015).
tumor (continued). "Comparing colony formation between the cell lines showed a significant reduction in colony formation by 989 tumor cells after Grb10 expression as compared to control, which was rescued with co-expression of MEK DD with Grb10." (PMID 26000738, 2015). "As a negative regulator of Ras signaling, Grb10 also modulates PI3K and MAPK signaling pathways, although our experiments involving untransformed MEFs and tumor cells suggest that the precise downstream effects may differ depending on context." (PMID 26000738, 2015). "In our study, restoration of wildtype Grb10 expression in Nf1 mutant tumor cells lacking Grb10 expression failed to suppress phosphorylation of S6Kinase upon exposure to insulin." (PMID 26000738, 2015). "Grb10 has not previously been shown to be intrinsically oncogenic either in vivo or in vitro, nor have tumor-promoting functions of mTOR, the best understood phosphorylator of Grb10, been shown to be Grb10-dependent." (PMID 26000738, 2015). "Expression analysis of tumor cell lines established from our mouse models identified Grb10 expression as widely absent." (PMID 26000738, 2015). "Grb10 is not known to have a role in tumor suppression, although Grb10 expression is reduced in a wide range of human cancers." (PMID 26000738, 2015). "The aneuploidic increases in copy number of genes that may promote tumor formation, including ARHGAP26, GRB10, DDHD2, FGFR1, CTNNA3, PTPN1 and MLLT1 in the apparently stable and karyotypically normal lines HS293 and HS401, are cause for concern." (PMID 20428235, 2010). "Genes such as BCL7A and GRB10 may exert anti-cancer effects by promoting immune cell infiltration, whereas KLRG1, THEM4, and TDRD9 might suppress immune cell infiltration, facilitating tumor progression." (PMID 39867577, 2024). "For example, overexpression of GRB10 and TDRD9 may enhance cancer cell proliferation, while downregulation of BCL7A, GPR18, KLRG1, and THEM4 could contribute to reduced immune surveillance and tumor evasion." (PMID 39867577, 2024). "Similar to Grb10, Grb2, Grb7 and Grb14 expression varied among different control organs examined, however none were overexpressed in any tumor cell line compared to control tissues, arguing against compensatory overexpression of Grb family members in response to reduced Grb10 expression." (PMID 26000738, 2015). "Grb10-overexpressing V16HRas-transformed human astrocytes demonstrated sustained phosphorylated ERK, in contrast to the Nf1 mutant tumor cell line 881, which similar to the 989 tumor cell line showed significantly reduced MAPK signaling and slightly reduced Akt phosphorylation." (PMID 26000738, 2015). "To determine whether Grb10-mediated suppression of colony formation by tumor cells requires inhibition of MAPK signaling, we expressed a constitutively activated Flag tagged-MEK (MEK DD) alone or with wildtype Grb10 in 989 tumor cells." (PMID 26000738, 2015). "This difference between HEK293 cells and our Nf1 mutant tumor cells may reflect the possibility that a Grb10-mediated negative feedback loop acting upon mTOR also requires fully intact Ras regulation, such as neurofibromin." (PMID 26000738, 2015). "To determine whether MEF hyperproliferation after Grb10 silencing, similar to tumor cells, involved Grb10-dependent effects on Ras signaling, we used phospho-specific immunoblotting to assess Ras effector activation in the presence or absence of Grb10 silencing." (PMID 26000738, 2015).
cancer (19 papers, 2012 to 2025). A tumor composed of atypical neoplastic, often pleomorphic cells that invade other tissues. "GRB10 has most often been studied for its pro-proliferative role in different cancers; increased expression of GRB10 being associated with tumorigenesis." (PMID 39223679, 2024). "And overexpression of miR-379-5p mimic in cells significantly reduced the increase of cancer malignancy caused by GRB10 upregulation." (PMID 37179120, 2023). "GRB10 encodes a growth receptor bound protein that plays an important role in multiple key cancer signalling pathways such as the Wnt and Akt pathways." (PMID 31093489, 2019). "Grb10 expression is reduced in a variety of human cancers, although the underlying mechanism for this reduction has not been defined." (PMID 26000738, 2015). "Interestingly, Grb10 is frequently downregulated in various human cancers, with the loss of Grb10 and PTEN being mutually exclusive." (PMID 22666248, 2012). "In addition, non-genetic alternative mechanisms might be operational in human cancers promoted by GRB10 and NF1 co-loss." (PMID 26000738, 2015). "GRB10, meanwhile, is involved in regulating cancer onset and progression, encompassing critical aspects such as cell metabolism, growth, and apoptosis." (PMID 39926275, 2025). "A diagnostic tool to distinguish 10 cancers by two or more positive genes of gene classes (GNAS, GRB10, and SNRPN)." (PMID 38812777, 2024). "More and more studies have shown that the abnormal expression of GRB10 is closely related to the occurrence and development of cancer." (PMID 37179120, 2023). "For this investigation, we focused on the expression status of three imprinted genes—GNAS, GRB10, and SNRPN known to be associated with cancer status." (PMID 32448196, 2020). "To analyze the allelic expression of imprinted genes in cancer, we selected 5 imprinted genes GNAS, GRB10, SNRPN, IGF2, and IGF2R which were mostly reported to be associated with cancer." (PMID 32448196, 2020). "We therefore selected GNAS, GRB10, and SNRPN genes as the more efficient cancer biomarkers for our diagnostic model." (PMID 32448196, 2020). "This work identifies a novel link between cancer and Grb10, an imprinted gene involved in organismal metabolism and growth." (PMID 26000738, 2015). "However, recent in vitro and in vivo studies have shown that GRB10 is also involved in regulating the occurrence and development of cancer, including regulating cell metabolism, cell growth and apoptosis." (PMID 37179120, 2023). "Analysis of data from the TCGA database showed altered expression of GRB10 in most types of cancer." (PMID 37179120, 2023). "In this study, the expression of GRB10 in 24 types of cancers in the TCGA database was analyzed." (PMID 37179120, 2023). "The expression of GRB10 was found to be elevated in 10 types of cancer." (PMID 37179120, 2023). "The most frequently epimutated regions varied depending on tissue origin, with the maternally methylated ZNF597 DMR being affected in 66.6% of hepatocarcinoma cell lines, H19 in 28.9 % of lung, ZNF331 DMR1 in 32% of colon and GRB10 in 44.9% of breast-derived cancer cell lines." (PMID 28883545, 2017). "Both GRB10 and ZFAT are known to play a role in regulating hematopoietic stem cell self-renewal and haematopoiesis and several studies revealed an association with cancer progression." (PMID 28912427, 2017). "Conversely, in vivo loss of Grb10 in mouse models increases animal size due to hyperproliferation of peripheral tissues, although these animals have no apparent propensity to develop cancers." (PMID 26000738, 2015). "Given multiple potential mechanisms for Grb10 protein function, Grb10 protein levels may be more informative than genetic or transcript analysis alone in determining GRB10 status in human cancers." (PMID 26000738, 2015). "Thus, gene body methylation may be a mechanism by which to upregulate GRB10 in cancer cells, although the function of GRB10 in CRC remains to be clarified." (PMID 27977763, 2016).
cancer (continued). "Results indicated that core genes can influence cancer progression by regulating immune cells, with BCL7A and GRB10 showing positive correlations with immune cell infiltration in most cancers." (PMID 39867577, 2024). "Using these results, imprinted genes GNAS, GRB10, and SNRPN were identified as the more efficient cancer biomarkers over IGF2 and IGF2R, specifically using our QCIGISH method." (PMID 32448196, 2020). "For our study, all the GNAS, GRB10, and SNRPN genes shared a similar expression pattern in 753 cases of ten cancers." (PMID 32448196, 2020). "We further analyzed the expression of imprinted genes GNAS, GRB10, and SNRPN in 204 benign and 654 malignant samples across ten cancer types." (PMID 32448196, 2020). "In order to find useful and efficient cancer biomarkers for clinical applications, we generated the ROC curves for the GNAS, GRB10, SNRPN, IGF2, and IGF2R imprinted genes using the individual BAE, MAE, and TE measurements for all the different cancer types combined." (PMID 32448196, 2020). "In addition, the diagnostic models developed from the BAE, MAE, and TE measurements of the imprinted gene panel GNAS, GRB10, and SNRPN could provide important predictive information which are useful in early-stage cancer detection and personalized cancer management." (PMID 32448196, 2020).
bacterial infections (1 paper, 2025). "Among the genes, BMX and GRB10 are particularly associated with immune-regulating signaling pathways, while GADD45A is mainly involved in the defense response to bacterial infections." (PMID 40230692, 2025).
CNS tumors (1 paper, 2015). "Because the tumors isolated from our mouse models are non-CNS tumors, Grb10 expression would be derived from the maternal Grb10 allele." (PMID 26000738, 2015).
GRB10 also shares sentences with these, for which no sentence is quoted: Hyperinsulinemia (2 papers); achondroplasia (1); adrenocortical tumors (1); Anxiety (1); autism (1); cardiac arrhythmia (1); celiac disease (1); cholangiocarcinoma (1); colon adenocarcinoma (1); colorectal cancer (1); congestive heart failure (1); dwarfism (1); Ewing sarcoma (1); gastric adenocarcinoma (1); glioblastoma (1); growth disorder (1); hepatocellular carcinoma (1); Hirschsprung disease (1); Hypoglycemia (1); Immune Deficiency (1); Infertility (1); intellectual disabilities (1); intervertebral disc degeneration (1); kidney diseases (1); liver failure (1); lung adenocarcinoma (1); metabolic disorders (1); metabolic syndrome (1); neurological disorders (1); non-alcoholic fatty liver disease (1).
A further 3 diseases each share a sentence with GRB10 in 1 paper.